KDM3A (lysine demethylase 3A)
Diseases named in the same sentence as KDM3A in open-access papers (continued):
Sharing a sentence is not in itself a finding about the gene and the disease.
myeloma (5 papers, 2016 to 2024). "Of interest, KDM3A restoration is the base to acquire an anti-apoptotic phenotype of myeloma cell apoptosis in chronic hypoxia through accumulating HIF-1α." (PMID 34044859, 2021). "Interestingly, in our analysis, only in-frame insertions were found in KDM3A, which acts as an epigenetic regulator via the demethylation of downstream targets contributing to myeloma cell survival." (PMID 39769182, 2024). "Previous studies have reported an elevated KDM3A in myeloma cells in response to a decrease in H3K9me2 expression and that KDM3A could stimulate autophagy by suppressing H3K9me2 levels." (PMID 37305393, 2023). "KDM3A is implicated in tumorigenesis; however, its biological role in multiple myeloma (MM) has not been elucidated." (PMID 26728187, 2016). "Here, the authors reveal a role for the histone demethylase KDM3A in the survival of this haematologic cancer, and show that mechanistically KDM3A removes H3K9 methylation from the promoters of KLF2 and IRF4, genes essential for myeloma cell survival." (PMID 26728187, 2016).
glioblastoma (4 papers, 2018 to 2024). The most malignant astrocytic tumor (WHO grade IV). "Glioblastoma-EV-packaged miR-27a-3p could promote M2 macrophage polarization via the EZH1/KDM3A/CTGF axis, and contribute to glioblastoma cell proliferation and motility, thereby increasing GSC tumorigenicity in vivo." (PMID 38379858, 2024).
liver cancer (4 papers, 2020 to 2025). An epithelial or non-epithelial malignant neoplasm that arises from the liver. "Moreover, a high CEP131 or KDM3A level was associated with poor overall survival in liver cancer patients." (PMID 36008383, 2022). "Furthermore, KDM3A is linked to oncogenic pathways in liver cancer." (PMID 32354028, 2020). "In the present study, we demonstrated that ARID3A and CEP131 co-occupy the promoter region of KDM3A and contribute to its transcriptional activity, ultimately enhancing liver cancer cell oncogenic ability." (PMID 36008383, 2022). "Overexpression of either ARID3A or CEP131-induced KDM3A mRNA expression in liver cancer cells, and this induction was abolished by silencing either CEP131 or ARID3A." (PMID 36008383, 2022). "Both the mRNA and protein levels of KDM3A were increased upon CEP131 overexpression, while knockdown of CEP131 reduced KDM3A expression, suggesting that KDM3A is also a downstream target of CEP131 in liver cancer cells." (PMID 36008383, 2022). "ARID3A and CEP131 promote an ES cell gene signature through activation of KDM3A and contribute to the poor prognosis of liver cancer patients." (PMID 36008383, 2022). "ARID3A interacts with CEP131 and co-occupies the KDM3A promoter region to activate KDM3A transcription, thereby modulating the expression of ES signature genes in liver cancer cells." (PMID 36008383, 2022). "During hypoxia, KDM3A demethylates H3K9me2 and allows chromatic relaxation for adrenomedullin transcription, which enhances the proliferative properties of liver cancer cells." (PMID 34200849, 2021). "KDM3A demethylates mainly the repressive mark H3K9me2 in liver cancer cells." (PMID 36008383, 2022). "Furthermore, knockdown of KDM3A led to a reduction in the levels of ARID3A-associated ES genes, suggesting an active role for KDM3A in mediating the expression of these genes in liver cancer." (PMID 36008383, 2022). "Interestingly, ARID3A can regulate the expression of KDM3A, thereby driving the expression of ES signature genes through H3 lysine 9 dimethylation (H3K9me2) in liver cancer cells." (PMID 36008383, 2022). "Furthermore, the mRNA level of KDM3A correlated significantly with that of CEP131 in liver cancer patients based on data from the TCGA-LIHC cohort." (PMID 36008383, 2022). "KDM3A depletion suppresses liver cancer cells tumorigenicity in nude xenograft mice models." (PMID 34200849, 2021). "The results showed that KDM3A knockdown strikingly decreased the migration, invasion and tumoursphere formation of ARID3A-overexpressing liver cancer cells." (PMID 36008383, 2022). "ARID3A can cooperate with CEP131 to transcriptionally activate KDM3A and promote expression of ES signature genes, suggesting that ARID3A and CEP131 are potential targets for the development of new anticancer therapeutics for liver cancer." (PMID 36008383, 2022).
lung adenocarcinoma (4 papers, 2018 to 2021). A carcinoma that arises from the lung and is characterized by the presence of malignant glandular epithelial cells. "Despite these results that support the role of KDM3A in evading the immune system, further studies are needed to fully clarify its role in promoting lung adenocarcinoma growth." (PMID 32354028, 2020). "Upregulation of TLR4 significantly increases the expression of KDM3A in A549 lung adenocarcinoma cells, which subsequently controls Foxp3 transcription." (PMID 32354028, 2020). "KDM3A is suggested to aid lung adenocarcinoma cells in evading the immune system of patients by upregulating forkhead box P3 (Foxp3) expression in regulatory T cells (Tregs)." (PMID 32354028, 2020). "Significant evidence confirming the role of KDM3A in lung adenocarcinoma has been reported, and KDM3A might be the target gene of miR-let-7 based on bioinformatics data." (PMID 33816782, 2021). "Similarly to rescued shG9a adenocarcinoma cells, we observed significant downregulation of the G9a targets Sca-1 and Mmp10, suggesting that Kdm3a depletion may impede TPCs through the same mechanisms as G9a expression in lung adenocarcinoma cells." (PMID 30455465, 2018).
lymph node metastasis (4 papers, 2016 to 2024). "The results showed that patients with elevated KDM3A expression tended to have greater tumor invasion and lymph node metastasis." (PMID 39031630, 2024). "The elevated KDM3A expression positively correlates with the invasion depth and lymph node metastasis, suggesting that Kdm3a may be an independent prognostic predictor of overall survival." (PMID 29156681, 2017).
sarcoma (4 papers, 2016 to 2022). A usually aggressive malignant neoplasm of the soft tissue or bone. "We therefore predicted genes having positive correlations with KDM3A in sarcoma tissues in the UALCAN system, and those having an over 0.5 correlation coefficient were selected for subsequent use." (PMID 35590288, 2022). "Together, our studies reveal an important role for the KDM3A/Ets1/MCAM axis in pediatric sarcomas of distinct cellular and molecular ontogeny, and identify new targetable vulnerabilities in RMS." (PMID 32577157, 2020). "To evaluate a potential role of KDM3A in sarcoma dissemination, we used a transendothelial invasion assay, which assesses the ability of cells to traverse endothelium during the metastatic steps of vascular intravasation and extravasation." (PMID 32577157, 2020). "To probe potential roles of KDM3A in RMS progression, we turned to assays evaluating properties related to sarcoma growth and dissemination." (PMID 32577157, 2020). "Our own recent studies identified the epigenetic regulator KDM3A (JMJD1A/JHDM2A), a member of the Jumonji C domain-containing histone demethylase (JHDM) family, as a disease-promoting factor in a pediatric sarcoma." (PMID 32577157, 2020).
breast tumor (3 papers, 2016 to 2017). "In agreement with the notion that Kdm3a can promote breast tumor growth, we found that the proliferation rate of WT tumor cells was much higher than that of Kdm3a KO tumor cells." (PMID 29156681, 2017). "All these results demonstrated that KDM3A/JMJD1A regulates breast tumor transformation through directly binding MYC and PAX3 oncogenes and modulating their transcription." (PMID 27034728, 2016). "Furthermore, we identified that KDM3A/JMJD1A, an H3K9me2 demethylase, is responsible for the H3K9me2 reduction and critical for breast tumor transformation." (PMID 27034728, 2016).
cervical cancer (3 papers, 2016 to 2023). A primary or metastatic malignant neoplasm involving the cervix. "KDM3A is an epigenetic regulator that has been found to be highly expressed in cervical cancer tissues and involved in cervical cancer progression." (PMID 35574500, 2022). "Similarly, the miR-148a-3p/c-Met axis and the miR-let-7e/KDM3A/p21 axis contribute to the formation and development of cervical cancer and NSCLC." (PMID 36672893, 2023).
esophageal squamous cell carcinoma (3 papers, 2020 to 2023). Esophageal squamous cell carcinoma (ESCC) is a type of esophageal carcinoma (EC) that can affect any part of the esophagus, but is usually located in the upper or middle third. "Relevantly, radiotherapy resistance of esophageal squamous cell carcinoma, promoted by hypoxia, has been shown to occur through increased expression of KDM3A and KDM6B." (PMID 35625569, 2022). "Under hypoxia, KDM3A was increased and co-localized with hypoxia-inducible factor HIF-1α in esophageal squamous cell carcinoma (ESCC)." (PMID 36797239, 2023).
Insulin resistance (3 papers, 2018 to 2024). Increased resistance towards insulin, that is, diminished effectiveness of insulin in reducing blood glucose levels. "For example, the knockout mouse model of the H3K9-specific demethylase KDM3A (also known as JHDM2A or JMJD1) leads to adipose tissue accumulation and insulin resistance." (PMID 30567372, 2018).
leukemia (3 papers, 2018 to 2023). A malignant (clonal) hematologic disorder, involving hematopoietic stem cells and characterized by the presence of primitive or atypical myeloid or lymphoid cells in the bone marrow and the blood. "Using qPCR validation, we confirmed that the expression of Kdm3a was progressively upregulated in Dox-treated leukemia cells but not in normal HSPCs." (PMID 31811153, 2019).
myocardial ischemia (3 papers, 2022 to 2025). A disorder of cardiac function caused by insufficient blood flow to the muscle tissue of the heart. "Our prior studies have characterized the participation of histone demethylase KDM3A in diabetic vascular remodeling, while its roles in myocardial ischemia/reperfusion (I/R) injury (MIRI) remain to be illustrated." (PMID 35338235, 2022).
renal fibrosis (3 papers, 2020 to 2021). A final common manifestation of a wide variety of chronic kidney diseases characterized by glomerulosclerosis and tubulointerstitial fibrosis. "In a previous study, microRNA-101 inhibited renal fibrosis by inhibiting KDM3A expression to regulate TGIF1 expression." (PMID 33414721, 2020). "Based on the results obtained, we suggested that miR-101a overexpression could inhibit renal fibrosis via suppression of KDM3A." (PMID 32092824, 2020). "KDM3A has been detected to downregulate the expression of TGIF1 in renal fibrosis." (PMID 32092824, 2020). "In order to elucidate the effect of KDM3A on renal fibrosis, HK2 cells were transfected with short hairpin RNA (sh)-KDM3A and overexpression (oe)-KDM3A." (PMID 32092824, 2020). "Interestingly, lysine-specific demethylase 3A (KDM3A) enhanced transforming growth factor β-induced factor 1 (TGIF1), inhibited fibronectin, alpha skeletal muscle actin (α-SMA) as well as the phosphorylation of Smad2/3 to curtail renal fibrosis." (PMID 33414721, 2020). "Treatment of miR-101a agomir + oe-KDM3A showed increased fibrosis degree of kidney tissues in UUO mice when compared to miR-101a agomir + oe-NC treatment, indicating that overexpression of KDM3A could reverse the inhibitory effect of upregulated miR-101a on renal fibrosis." (PMID 32092824, 2020). "In addition, miR-101a could target and downregulate KDM3A expression, which led to elevated TGIF1, inhibited expression of Collagen I (Col1a1), fibronectin, α-SMA, YAP1, and TGF-β2 along with the extent of Smad2/3 phosphorylation, as well as delayed renal fibrosis degree." (PMID 32092824, 2020).
rhabdomyosarcoma (3 papers, 2020 to 2025). A rare aggressive malignant mesenchymal neoplasm arising from skeletal muscle. "In rhabdomyosarcoma (RMS), the KDM3A/Ets1/MCAM axis has been identified as a key pathway, in which KDM3A promotes the expression of MCAM, contributing to tumor growth and metastasis." (PMID 41388158, 2025).
acute myeloid leukemia (2 papers, 2023 to 2024). Acute myeloid leukemia (AML) is a group of neoplasms arising from precursor cells committed to the myeloid cell-line differentiation. "We also found that KDM3A is related to both PAC-1 and the human acute myeloid leukemia (AML) cell line NOMO1." (PMID 37072452, 2023).
autoimmune disease (2 papers, 2013 to 2024). A disorder resulting from loss of function or tissue destruction of an organ or multiple organs, arising from humoral or cellular immune responses of the individual to their own tissue constituents. "Despite a lack of Kdm3a influence on basic immune phenotypes, we tested if Kdm3a had an effect on EAE as immune functions can be quite specific in the context of an autoimmune disease." (PMID 24312603, 2013). "Our results demonstrated that Kdm3a has no impact on activation or susceptibility to an autoimmune disease." (PMID 24312603, 2013).
embryonal carcinoma (2 papers, 2013 to 2017). A non-seminomatous malignant germ cell tumor characterized by the presence of large germ cells with abundant cytoplasm resembling epithelial cells, geographic necrosis, high mitotic activity, and pseudoglandular and pseudopapillary structures formation. "For example, the hypoxia-induced KDM3A expression was found to be markedly reduced in human germ cell-derived tumors including seminomas, yolk sac tumors, and embryonal carcinomas." (PMID 29156681, 2017). "Intriguingly, Kdm3a was also reported as a tumor suppressor in human germ cell-derived tumors such as seminomas, yolk sac tumors and embryonal carcinomas." (PMID 29156681, 2017).
glioma (2 papers, 2023 to 2026). A benign or malignant brain and spinal cord tumor that arises from glial cells (astrocytes, oligodendrocytes, ependymal cells). "Therefore, we sought to validate the potential association and functionality of NURP1/KDM3A/TFEB in the context of TMZ resistance in glioma cells." (PMID 37305393, 2023). "Therefore, miRNAs and transcription factors may be implicated in the upstream mechanism of KDM3A in glioma development." (PMID 37305393, 2023). "In this study, we evaluated the effects of nuclear protein-1 (NURP1) on TMZ resistance in hypoxia-treated glioma cells by modulating autophagy via the KDM3A/TFEB axis." (PMID 37305393, 2023). "For a comprehensive understanding of the effector of the KDM3A/NURP1 axis in glioma cell autophagy, it is vital to consider the role of TFEB in mediating the autophagy-lysosome system in various tumors." (PMID 37305393, 2023). "Collectively, these findings support the role of NUPR1 in promoting cell autophagy to reduce TMZ resistance in glioma in vivo via the KDM3A/TFEB axis." (PMID 37305393, 2023). "By investigating the potential association and roles of NURP1/KDM3A/TFEB, we aim to provide new insights into the molecular route of TMZ resistance in glioma cells." (PMID 37305393, 2023). "Our results suggest that hypoxia-induced NUPR1 promotes TFEB transcription by binding to KDM3A and reducing H3K9me2 levels, thereby augmenting glioma cell autophagy and TMZ resistance." (PMID 37305393, 2023). "Nevertheless, the role of KDM3A in glioma from perspective of resistance to TMZ remains elusive." (PMID 37305393, 2023). "Collectively, our findings indicate that hypoxia could reduce H3K9me2 expression in glioma cells by promoting the binding of NURP1 to KDM3A." (PMID 37305393, 2023). "Moreover, the overexpression of KDM3A or TFEB promoted glioma cell autophagy." (PMID 37305393, 2023). "This is due to the evidence that NUPR1 promotes glioma cell autophagy and TMZ resistance via the KDM3A/TFEB axis." (PMID 41596413, 2026). "Overall, our findings highlight a mechanism by which NUPR1 enhances glioma cell autophagy and TMZ resistance via the KDM3A/TFEB axis." (PMID 37305393, 2023). "In essence, our experimental findings validated that NUPR1 binding to KDM3A reduces H3K9me2 levels and enhances TFEB transcription, leading to increased autophagy and augmenting TMZ resistance in hypoxia-treated glioma cells." (PMID 37305393, 2023). "In conclusion, the present study aims to investigate the potential regulatory role of NURP1 may regulate the KDM3A/TFEB axis to modulate autophagy under hypoxia, and this process may affect TMZ resistance in glioma cells." (PMID 37305393, 2023).
heart failure (2 papers, 2018 to 2024). Inability of the heart to pump blood at an adequate rate to meet tissue metabolic requirements. "Kdm3a-Tg TAC mice had more severe heart failure reflected by greater lung weight, more interstitial fibrosis than in WT-TAC, and worse cardiac function." (PMID 30531796, 2018). "Overexpression of lysine-specific demethylase 3A (KDM3A) leads to the up regulation of fibrosis-related genes COMP, COL8A1, and LOX and the down regulation of ACOT1, result in enhanced fibrosis and heart failure." (PMID 38854759, 2024).
Hyperinsulinemia (2 papers, 2020 to 2022). An increased concentration of insulin in the blood. "Moreover, our published research provided solid evidence that KDM3A functions as an upstream regulator of NF-κB/P65 and is implicated in hyperinsulinemia-caused VSMCs injury by aggravating inflammation, apoptosis, and ROS." (PMID 35571189, 2022).
injury (2 papers, 2022 to 2025). Damage inflicted on the body as the direct or indirect result of an external force, with or without disruption of structural continuity. "Finally, quercetin, a geroprotective small molecule, upregulates KDM3A protein expression and promotes adult hippocampal neurogenesis following brain injury." (PMID 40033066, 2025).
left ventricular hypertrophy (2 papers, 2018 to 2020). Enlargement of the LEFT VENTRICLE of the heart. "Here the authors show that KDM3A promotes left ventricular hypertrophy and cardiac fibrosis by activating the transcription of Timp1, and that pharmacological inhibition of KDM3A attenuates cardiac remodeling induced by pressure overload." (PMID 30531796, 2018).
metastatic disease (2 papers, 2020 to 2024). "In this model, stable depletion of KDM3A in the FP-RMS Rh30 cell line resulted in a significantly smaller metastatic disease burden, thus supporting a role for KDM3A in metastasis promotion in vivo." (PMID 32577157, 2020). "In addition, we found that in vivo experiments indicated that the growth, invasion and metastasis of metastatic neoplasms were significantly inhibited by knockout of KDM3A in a TNBC metastasis model." (PMID 38165573, 2024).
non-small cell lung carcinoma (2 papers, 2016 to 2021). A group of at least three distinct histological types of lung cancer, including non-small cell squamous cell carcinoma, adenocarcinoma, and large cell carcinoma. "The study mainly addressed the oncogenic role of long non-coding RNA SNHG4 in non-small cell lung cancer progression through the miR-let-7e/KDM3A/p21 axis, thus highlighting a potential therapeutic action against non-small cell lung cancer." (PMID 33816782, 2021).
prostate adenocarcinoma (2 papers, 2017 to 2018). "In prostate adenocarcinoma (PRAD), KDM3A functions as a transcriptional coactivator for the androgen receptor (AR; Gene ID: 367)." (PMID 28416760, 2017).
prostate tumor (2 papers, 2017 to 2020). "KDM3A knockdown abolished tumor formation in an orthotopic prostate tumor model using CWR22Rv1 cells." (PMID 28416760, 2017). "Moreover, in an orthotopic prostate tumor model using CWR22Rv1 cells with permanently activated AR, KDM3A knockdown disrupts tumor formation, highlighting the importance of KDM3A in androgen signaling and carcinogenesis." (PMID 32354028, 2020). "In the KDM3A-knockdown Rv1 xenograft prostate tumor model, tumor weight is decreased by 13-fold, whereas no tumor formation occurs in castrated mice." (PMID 32354028, 2020).